CD63 (CD63 molecule)
Diseases named in the same sentence as CD63 in open-access papers (continued):
Sharing a sentence is not in itself a finding about the gene and the disease.
cancer (continued). "SNAP23 was reported to promote MVB fusion with the plasma membrane, resulting in CD63-positive exosome release after its phosphorylation on Ser110; different studies have shown a colocalization of both SNAP23 and LC3 with the exosomal marker CD63 within MVB-like structures in cancer cells." (PMID 35008395, 2022). "CD63 (also known as lysosome-associated membrane glycoprotein, LAMP3), as the general tetraspanin protein, has been identified as the exosomal ‘star marker’ and overexpressed on the surface of exosomes from cancers." (PMID 36431072, 2022). "However, when CD63 antibody and MB-21 were added to the cancer EVs, followed by flow cytometric analysis, the CD63 positive EVs increased to 19.2%, while the miR-21 positive EVs among cancer EVs increased to 30.2%." (PMID 33477255, 2021). "This article reviewed the characteristics and functions performed individually by TIMP1, CD63, and β1-integrin, the roles of the TIMP-1/CD63/β1-integrin complex, both in a physiological context and in cancer, and the regulatory mechanisms involved in its assembly." (PMID 34502227, 2021). "Moreover, in recent years utility of aptamers has also been demonstrated to detect EVs from cancer cells by capturing the cells through aptamers targeting CD63, EpCAM, PDGF-β receptor or nucleolin." (PMID 35056102, 2021). "Moreover, cancer patients frequently have high levels of CD63-positive platelet-derived microparticles (PMPs), inducing a pro-coagulant cancer environment." (PMID 34322381, 2021). "However, elevated levels of CD63 have been found in patients with cancers and human immunodeficiency virus (HIV) infection." (PMID 33669497, 2021). "That is, although CD63 positive EVs (x-axis) in a sub-population were almost the same between normal and cancer EVs, cancer-related miRNA, miR-21 positive EVs (y-axis) increased in cancer EVs." (PMID 33477255, 2021). "Anti-CD44 and anti-CD63 antibodies were here used to capture cancer and generic EVs." (PMID 34855021, 2021). "In short, tetraspanin CD63 surround nuclear contents released by disrupted MN and load them into the exosomes, and nEXO may provide a novel insight for the cancer biomarker development." (PMID 34661500, 2021). "In this work, EVs from three different cancer types were captured with anti-CD63 magnetic beads, followed by the addition of three types of SERS nanotags (i.e. Raman reporter-detection antibody-decorated AuNPs targeting the EV membrane proteins glypican-1, EpCAM, and CD44)." (PMID 34855021, 2021). "Based on these results, we firmly believe that the developed aptamers could be useful towards efficient isolation of native state exosomes from clinical samples and various theranostic applications for CD63-positive cancers." (PMID 33261145, 2020). "In addition to being a confirmed cancer marker, in recent years, the importance of CD63 in exosome identification has been emphasized." (PMID 33261145, 2020). "Exosomes derived from targeted CD63-Antares2-expressing cancer cells could be a promising tool for evaluating the efficacy of exosome inhibitors in vivo." (PMID 33024173, 2020). "Taken together, these results indicated that the xenograft mouse model bearing CD63-Antares2-expressing cancer cells allows monitoring long-term circulating cancer-derived exosomes quantitatively and in a time-dependent manner, and visualizing exosome-homing organs, tissues, and cells." (PMID 33024173, 2020). "Common EV markers (CD63, TSG101) and disease-specific EV-associated proteins (PD-L1, GPC-1) were readily detected following isolation by the ACE chip from either spiked EV or donor cancer samples." (PMID 33224932, 2020). "The CD63-Antares2 xenograft mouse model might be useful for analyzing organotropism of cancer-derived exosomes in living animals, in a time-dependent manner." (PMID 33024173, 2020). "Furthermore, more in-depth studies are required as anti-CD9 and CD63 antibodies are unable to selectively target the cancer-derived EVs in humans." (PMID 31428232, 2019).
cancer (continued). "However, these CD9 or CD63 antibodies cannot selectively bind cancer-derived EVs; thus, further investigations to find cancer-specific antigens on the surface of EVs are needed." (PMID 31447954, 2019). "Analyzing scRNA‐seq data from platinum‐naïve cancer cells demonstrated a low‐COX7B subclone that could be sorted out from bulk cancer cells by assaying CD63." (PMID 30367559, 2018). "We visualized EVs from cancer cells using bioluminescence imaging and showed that several EVs could be observed when using CD63 fused with NanoLuc luciferase, which has a much smaller molecular weight and higher intensity than conventional firefly luciferase." (PMID 28929569, 2018). "Since CD63 expression in stromal cells was significantly correlated with CD63 expression on cancer cells, CD63-positive exosomes in the cytoplasm of stromal cells might be derived from the exosomes of cancer cells." (PMID 30222750, 2018). "Of 595 patients, 247 had CD63-positive cancer cells, and 107 had CD63-positive stromal cells." (PMID 30222750, 2018). "We revealed that assaying CD63 could sort out this subclone from bulk cancer cells, possibly stimulating the development of tailored treatments aiming to determine subclones of cancer cells in the clinic." (PMID 30367559, 2018). "CD63 expression in cancer cells and stromal cells was analyzed by immunohistochemistry." (PMID 30222750, 2018). "Whereas the role of CD63 in regulating cancer cell functions, such as cell activation, adhesion, differentiation and migration, is well-established in solid tumors, its role remain unclear as for hematological disease." (PMID 27903985, 2017). "In that study, EVs tagged by anti-CD9 and CD63 were internalized by macrophages via phagocytosis before they could promote cancer progression." (PMID 29238879, 2017). "Furthermore, both TSG101 and CD63 were detected in exosomes derived from all 3 different cancer cell lines." (PMID 27385095, 2016). "Furthermore, both Alix and CD63 were detected in exosomes derived from all 3 different cancer cell lines (lanes 2, 4 and 6)." (PMID 24831807, 2014). "Moreover, several reports have shown that CD63 interacts with many different proteins, including integrins and the Src family tyrosine kinases Lyn and Hck, which are known to promote cancer malignancy." (PMID 24884960, 2014). "CD63, a member of the tetraspanin membrane protein family, plays a pivotal role in cell growth, motility, signal transduction, host-pathogen interactions and cancer." (PMID 24132157, 2013). "Immunoaffinity capture methods can be used to isolate exosomes from cancer cells or patient serum using beads coated with antibodies against presumably any exosome-specific surface marker, such as the tetraspanins, CD63 or CD82, as a way to forego any ultracentrifugation." (PMID 23839094, 2013). "CD63 may then serve as an important therapeutic target against the cancer types with elevated stroma TIMP-1 levels." (PMID 24143225, 2013). "Carcinomas in M0 stage revealed a stronger expression of CD63 than carcinomas in M1 stage." (PMID 21521534, 2011). "Interestingly, despite the inter‐plasma variations amongst EVs of the same cellular origin, the change of fluorescence polarisation for the detection aptamer against CD63 can demarcate the EVs immobilised with anti‐EpCAM antibody from three different cancer cells." (PMID 39221546, 2024). "Therefore CD63+-EVs was shown to respond to neurodenegerative disorders as well as cancers." (PMID 35350978, 2022). "In addition, VEGF in cancer cell-derived EVs have also been identified, and tetraspanin CD63 might participate in the packaging of VEGF into cancer EVs38." (PMID 36528739, 2022). "In addition, previous research has shown that CD63 is one of the possible prognostic indicators for patients with GC, since CD63-positive exosomes may be related to the interaction between stromal cells and cancer cells." (PMID 35173726, 2022).
cancer (continued). "Interestingly, our data suggested that cells with the highest m7G score also exhibited a high expression level of microglia/macrophage markers CD63, and these cells were predicted to communicate with a cluster of cells with high expression of cancer stem cell maker THY1 via PTN pathway." (PMID 36036011, 2022). "However, the knowledge about the role of CD63 N-glycosylation in cancer is still limited." (PMID 34502227, 2021). "Because all these processes are critical for cancer progression, our observation warrants further research on the molecular mechanisms that mediate this Tz effect and possible functional implications of the inclusion of CD63 50 kDa isoform in exosomes released by ERBB2+ BCa cells." (PMID 33809102, 2021). "However, this experiment strategy of targeting human CD9 and CD63 is only applicable in a xenograft nude mouse model for selectively eliminating human cancer sEVs from the blood, since CD9 and CD63 are expressed in sEVs released from both noncancerous and cancerous cells in humans." (PMID 32847103, 2020). "In addition, CD63-positive exosomes from stromal cells might stimulate the malignant potential of cancer cells." (PMID 30222750, 2018). "However, the contribution of glycosylation of CD63 to cancer malignancy is poorly understood." (PMID 24884960, 2014). "The binding interactions between immobilized antibodies and EVs isolated from different cancer cell lines revealed a unique SPR molecular fingerprint (SPR-MFP) consisting of varying expression levels of the CD9, CD63 and CD81 EV biomarkers, as well as CXCR4." (PMID 41892066, 2026). "It should be noted that the same proteins (CD9, CD24, CD63, CD81, MMP9) were common to exosomes of cancer cells and primary cells." (PMID 40310419, 2025). "This strategy enabled the detection of surface proteins (e.g., CD63, EpCAM, PSMA, and Nucleolin) on exosomes from various cancer cell lines, including HepG2, MCF-7, HeLa, HEK-293T, and L-02 cells." (PMID 39943486, 2025). "Through SDS-PAGE analysis, we discovered that the ratio of CD63 to CD81 in different EVs is consistent and distinct, making it a reliable characteristic for recognizing EVs secreted by cancer cells." (PMID 39194595, 2024). "Our investigation revealed that the exosome‐dominated EV subpopulation (Exo), captured using a combination of CD63/CD9/CD81 antibodies, proved effective as an mRNA‐based cancer marker." (PMID 38204202, 2024). "Higher expression of HIF1A, ABCA1, FPR1, CD63, and FCN1 was found in cancer compared to healthy state." (PMID 39315092, 2024). "In cancer, exosomes have been shown to carry specific proteins, such as CD63 and CD81, that are often upregulated in cancer cells, as well as specific miRNAs and mRNAs that can be used to monitor disease progression and treatment response." (PMID 38845750, 2024). "On the other hand, exosomal proteins, such as CD63, CD9, TSG101, and EpCAM, reflecting significant information about the cancer microenvironment, are highly enriched in exosomes derived from cancer cells." (PMID 38005527, 2023). "The interaction of TIMP1 protein’s C-terminal structural domain with tetraspanin CD63 stimulates conformational activation of integrin b1 and activates MAPK signaling, resulting in cancer." (PMID 36816016, 2023). "Altogether, these data confirm the ability of ALDH1A1:CD63-eGFP and SRE:CD63-eGFP expression cassettes to restrict expression of the tEV reporter within the CSC-enriched subpopulation of mEER and MOC2 cancer cell lines." (PMID 36735677, 2023). "The following TSPANs have been involved in enhancing cancer therapy resistance: CD9, CD81, TSPAN1, TSPAN3, TSPAN31, CD82 and CD63." (PMID 36941633, 2023). "Tetraspanins, includingCD9, CD63, and CD81, are transmembranebiomarkers that play a crucial role in regulating cancer cell proliferation,invasion, and metastasis, as well as plasma membrane dynamics andprotein trafficking." (PMID 37307147, 2023).
cancer (continued). "WB showed that the protein expression of exosome markers, Alix, CD9, and CD63, was increased in NC and ferroptosis-induced MDA-MB-231 cell and 4T1 cell-derived exosomes compared with corresponding cancer cells." (PMID 36949762, 2023). "Eleven of those proteins were detected in all patients, including the common EV markers CD9, CD63 and CD81, cancer-related markers CD24, CD29, CD44 and CD146, platelet markers CD41b, CD42a and CD62p as well as HLA-DR/DP/DQ." (PMID 35012489, 2022). "Overall, we demonstrated that the surface markers CD9, CD63, and CD81 are sufficient to distinguish between sEV populations derived from different cancer cells." (PMID 35955677, 2022). "Among these 16 proteins, proteins reflecting the cellular origin (HLA-DR, HLA-DP, HLA-DQ, CD31, CD41b, CD42a), activation markers (CD62p), EV markers (CD9, CD63, CD81), and cancer related markers (CD44 CD29, CD105, CD146) were found." (PMID 35012489, 2022). "A number of EV membrane proteins, including CD147/basigin and EpCAM, have been selected to pair with the EV markers CD9 or CD63 as biomarker panels for CRC and have been successfully tested for effective cancer detection using blood specimens." (PMID 36612172, 2022). "Exosomes labelled by CD63 and miRNA mimics labelled by Cy-3 were localized and observed under laser confocal microscopy in GES-1, indicating that cancer cell-derived exosomes can transfer miR-195-5p and miR-211-5p into recipient cells." (PMID 34422636, 2021). "The common exosome markers, including CD63, CD81, and CD9 and the cancer marker EGFR, are detected in A549 cell-derived exosomes with a Western Blot." (PMID 34769444, 2021). "Four bio-orthogonal click probes modified with trans-cyclooctene (TCO) were designed to enable the specific targeting of three cancer proteins (EGFR, EpCAM and MUC1) and one generic EV marker (CD63)." (PMID 34855021, 2021). "LMP1 reversibely increases the secretion of CD63-positive sEVs, furthermore, the knockdown of CD63 in cells could cause the reduction of LMP1 in sEVs, suggesting that CD63 may be associated with LMP1 sorting into sEVs, which supplies novel therapeutic targets to treat the EBV-associated cancers." (PMID 34661500, 2021). "CD63, β1-integrin, and TIMP-1 are among glycoproteins already identified as targets for aberrant N-glycosylation in cancer." (PMID 34502227, 2021). "CD9 (Tspan29), CD63 (Tspan30) and CD82 (Tspan27) inhibit metastasis of various cancers, whereas Tspan8 and CD151 (Tspan24) promote metastasis." (PMID 33955149, 2021). "Previous studies revealed a correlation between TIMP-1 expression and poor prognosis in cancer, and the structure-function interaction of TIMP-1 and CD63 has been demonstrated in live cells." (PMID 34611125, 2021). "EVs were isolated from 80 serum samples from healthy individuals and cancer patients via polyethylene glycol (PEG)-based precipitation and immunoaffinity separation using antibodies against CD9, CD63, CD81, and EpCAM." (PMID 33808296, 2021). "Many explanations exist for this contradictory phenomenon, such as the interaction between TIMP1 and CD63 to activate MAPK signalling and participation in the HGF/c-Met pathway to promote cancer progression." (PMID 34781885, 2021). "For the development of exosome-based early diagnosis and analysis of cancers, tetraspanins (such as CD9, CD63, CD81, and CD82) are typically utilized as the capturing molecules for the detection of cancer-associated exosomes." (PMID 33803846, 2021). "The expression levels of exosomal proteins, such as CD63, CEA, GPC-3, PD-L1 and HER2, were used to classify different cancer cell lines." (PMID 32802193, 2020). "In the PC3/CD63-Antares2 xenograft model mice, PC3 cancer cell-derived exosomes selectively accumulated in the lungs, spleen, lymph nodes, and adipose tissues after long-term circulation." (PMID 33024173, 2020).
cancer (continued). "Various exosome types circulate in the blood of healthy donors and patients with different cancers, and surface proteins mainly represented by CD9, CD24, CD63 and CD81 are considered as universal markers of blood exosomes." (PMID 32218180, 2020). "In terms of their potential impact in cancer, it is known that EV-derived TIMP-1 binds to CD63 and β1 integrin, which induces survival signals and promotes metastatic niche formation." (PMID 32610589, 2020). "Tetraspanins, a family of membrane scaffold proteins, CD63, and CD81 are also potential biomarkers for cancer." (PMID 30987213, 2019). "EBV can hijack cancer-derived EVs production to regulate cell-to-cell communication and package viral components, such as LMP1 and CD63, which modulate the TME and promote tumor development." (PMID 30954079, 2019). "Our results offer a new transcriptome landscape of platinum‐resistance that provides valuable insights into chemosensitivity and drug resistance in cancers, and we identify a novel platinum resistance gene, COX7B, and a surrogate marker, CD63." (PMID 30367559, 2018). "To image exosomes transferred from cancer cells to macrophages, we performed direct co-culture of MDA-MB-231/CD63-RFP cells and macrophage RAW264.7 cells." (PMID 29484119, 2018). "Proteomic profiling of extracellular vesicles of 60 cancer cell lines (NCI-60) revealed CD81 expression in all 60, while CD9 and CD63 were expressed in about 40 of these cell lines." (PMID 29946318, 2018). "Among the human tetraspanins, Tspan8 and 12, CD9, CD37, CD63, CD81, CD82, and CD151 play a role in cancer progression." (PMID 29946318, 2018). "CD9, CD63 and CD81 are expressed in many different types of cells including neural cells, cancer cells and cancer stem cell lines." (PMID 25682864, 2015). "However, the contribution of glycosylation of CD63 to cancer malignancy remains unclear." (PMID 24884960, 2014). "In conclusion, this study provides evidence of a novel and important function of RPN2-mediated glycosylation of CD63 in the regulation of MDR1 localization and cancer malignancy, including drug resistance and invasiveness." (PMID 24884960, 2014). "We revealed that CD63 interacts with MDR1 and regulates the drug resistance and invasiveness involved in cancer cell malignancy." (PMID 24884960, 2014). "The panel of antibodies contained the well-known exosome markers (CD9, CD63, CD81 and HLA-ABC) and 17 other membrane markers and antigens related to, for example, cancer and inflammation." (PMID 26082317, 2013). "By employing RT-PCR and immunohistochemistry, we studied the expression of CD9, CD63 and CD82 in 49 paired tissue specimens of normal gastric mucosa and carcinoma." (PMID 21521534, 2011). "Our findings build on this emerging evidence and suggest that PTGFRN may serve as a pan‐cancer marker of EVs derived through non‐canonical, ESCRT‐independent pathways—distinct from the classical CD9‐, CD63‐, or CD81‐marked small EVs." (PMID 41039818, 2025). "They found elevated levels of CD63 in exosomes derived from malignant cancer cells compared to those from non-cancerous cells, further supporting CD63 as a protein marker for cancer." (PMID 39148736, 2024). "In PDy, the up-regulation of CD63 aims to inhibit the development of the metastatic potential and mobility of dysplastic cells while simultaneously inhibiting the proteolysis of ECM against cancer progression." (PMID 39273632, 2024). "The tetraspanin family member was also found helpful in carrying out comparison of various human cancers; when quantification data showed lower levels of CD63 in exosomes derived from non-cancer cells." (PMID 36032679, 2022). "Similarly, we observed phase-shifted transcript pairs from cancer hallmarks genes like HRAS and CD63 unique to HCT116_PER2KO." (PMID 35552415, 2022).